FLNC (filamin C)
Diseases named in the same sentence as FLNC in open-access papers (continued):
Sharing a sentence is not in itself a finding about the gene and the disease.
restrictive cardiomyopathy (14 papers, 2019 to 2026). A type of heart disorder referring to the inability of the ventricles to fill with blood because the myocardium (heart muscle) stiffens and looses its flexibility. "In recent years, mutations of FLNC have been linked to different forms of genetic cardiomyopathies including dilated, arrhythmogenic, hypertrophic, and restrictive cardiomyopathy." (PMID 39858621, 2025). "Mutation ΔPGL leads to the deletion of tripeptide PGL in the structure of the 24th immunoglobulin-like domain of FLNC and is associated with restrictive cardiomyopathy." (PMID 40564978, 2025). "Recently, a novel pathogenic FLNC variant has been identified in a large French-Canadian family resulting in a severe phenotype of a mixed hypertrophic–restrictive cardiomyopathy." (PMID 39858621, 2025). "Among the subtypes, restrictive cardiomyopathy is characterized by restriction of ventricular filling and its uncommon cause is a disease due to mutation on Filamin C (FLNC) gene." (PMID 39764157, 2024). "As a consequence, missense and loss-of-function mutations in the FLNC gene have been associated with a variety of cardiomyopathies, including dilated, hypertrophic and restrictive cardiomyopathies, and myopathies." (PMID 38474188, 2024). "The present description of twelve cases of early-onset restrictive cardiomyopathy with congenital myopathy and FLNC mutation, underlines a distinct unique phenotype that can be suggested as a separate clinical form of filaminopathies." (PMID 36104822, 2022). "Except for DCM, some FLNC mutations were also related to hypertrophic and restrictive cardiomyopathies." (PMID 33941202, 2021). "Here, we described the impact of two clinically distinct FLNC variants (R1267Q associated with arrhythmogenic cardiomyopathy and V2264M associated with restrictive cardiomyopathy) on calcium homeostasis, electrophysiology, and gene expression profile of iPSC‐derived patient‐specific cardiomyocytes." (PMID 39315490, 2025). "In contrast, FLNC variants, leading to protein instability and formation of intracellular aggregates, are associated with MFM, hypertrophic or restrictive cardiomyopathy." (PMID 36104822, 2022). "Restrictive cardiomyopathy is a rare cardiac disease, for which several genes including TNNT2, MYPN, FLNC and TNNI3 have been associated with its familial form." (PMID 30953456, 2019). "FLNC variants have been associated with restrictive cardiomyopathy and non-compaction cardiomyopathies." (PMID 39764157, 2024). "Finally, inherited restrictive cardiomyopathies are caused by mutations in sarcomeric genes such as cardiac troponin I, and less commonly by mutations in Desmin (DES) and Filamin C (FLNC)." (PMID 37283586, 2023). "Since the truncating variants in FLNC are highly enriched in an overlapping phenotype of dilated and left-dominant arrhythmogenic cardiomyopathy, missense variants, especially those located in the ROD2 domain, have recently been associated with HCM and restrictive cardiomyopathy phenotypes." (PMID 38002985, 2023). "Variants predicted to lead to premature termination of translation in FLNC have been detected in individuals with dilated, arrhythmogenic, and restrictive cardiomyopathies, although this class of variant has not been widely reported in HCM patient cohorts (ACMG criteria PVS1_Strong10,14)." (PMID 30531895, 2019).
dilated cardiomyopathy (12 papers, 2014 to 2025). "From a genetic perspective, mutations in genes such as LMNA, SCN5A, and FLNC have been reported as forms of dilated cardiomyopathy associated with electrical instability." (PMID 40680495, 2025). "With over 80 heterozygous truncating mutations in FLNC associated with dilated cardiomyopathy, simulating each variant individually presents a significant challenge." (PMID 40099936, 2025). "We identified patients carrying frameshift variants of TTN (n = 2) and FLNC (n = 1), resulting in truncating proteins, which are classically associated with dilated cardiomyopathy, whereas the association of TTNtv with HCM has been reported only sporadically." (PMID 41440877, 2025). "Loss‐of‐function variants in the FLNC gene, which encodes Filamin C, cause dilated cardiomyopathy with a high risk of life‐threatening arrhythmias." (PMID 40099936, 2025). "Truncating mutations in filamin C (FLNC) are associated with dilated cardiomyopathy and arrhythmogenic cardiomyopathy." (PMID 38334670, 2024). "FLNC is among the most mutated genes in dilated cardiomyopathy (DCM) and hypertrophic cardiomyopathy (HCM) patients, underscoring the essential role of filamin C in cardiac development and function." (PMID 36706168, 2023). "One of the most mutated genes is FLNC (encoding filamin C), which has 77 variants identified among dilated cardiomyopathy (DCM) and 57 variants in hypertrophic cardiomyopathy (HCM) patients, many of which are pathogenic." (PMID 36706168, 2023). "In another mouse model, depletion of FLNc in the embryonic heart resulted in fetal death, while loss of FLNc in the hearts of adult mice caused severe dilated cardiomyopathy in most mice, leading to early death." (PMID 32887649, 2020). "Using OPEN, we prioritize genes, including FLNC, for association with increased left ventricular diameter, which is a defining feature of a prevalent cardiovascular disorder, dilated cardiomyopathy or DCM." (PMID 25633252, 2014). "Therapies targeting the underlying mechanism of FLNC‐related dilated cardiomyopathy remain limited." (PMID 40099936, 2025). "When we clustered the results, one PPI cluster for LVEF is dominated by genes previously implicated with dilated cardiomyopathy and heart failure risk (HSPB7, FLNC, ALPK3, CLCNKA), as well as links to the brain via WDR7391–97." (PMID 39670392, 2025). "Some special gene mutations in dilated cardiomyopathy such as DSP, LMNA, SCN5A, and FLNC have an arrhythmia rate of more than 30%35." (PMID 31953454, 2020). "Our findings suggest that PDI could be a promising therapeutic target for FLNC‐related dilated cardiomyopathy." (PMID 40099936, 2025). "MLP, like FLNC, is specific to striated muscle, and the phenotype of mice lacking MLP reproduces the morphology of dilated cardiomyopathy (DCM) and heart failure in humans." (PMID 31131323, 2019).
hypertrophic cardiomyopathy (12 papers, 2015 to 2023). A condition in which the myocardium is hypertrophied without an obvious cause. "FLNC, encoding filamin C, is one of the most mutated genes in dilated and hypertrophic cardiomyopathy." (PMID 36706168, 2023). "Mutations in filamin-C have been linked to hypertrophic cardiomyopathy, and its inducible knockout from cardiomyocytes causes a rapid decline in LV function." (PMID 37115698, 2023). "Missense variants in FLNC have been previously associated with skeletal muscle myofibrillar myopathy and hypertrophic cardiomyopathy, but recent studies identified FLNC truncating variants (FLNCtvs) as an important driver of arrhythmogenic DCM [67••]." (PMID 33040239, 2020). "In addition, studies have also found that mutations in the FLNC gene can cause hypertrophic cardiomyopathy." (PMID 38249550, 2023). "The variants in FLNC are mainly associated with Hypertrophic cardiomyopathy (not observed in patient 2 or the mother) and variants in AGRN are mainly associated with congenital myasthenic syndrome following an autosomal recessive pattern of inheritance." (PMID 37035729, 2023). "However, sequencing of FLNC gene from 540 hypertrophic cardiomyopathy (HCM) patients and 307 healthy controls, revealed that FLNC mutations are not rare, even in healthy controls, with a frequency of about 4%." (PMID 32295012, 2020).
Skeletal myopathy (12 papers, 2011 to 2024). "In the majority, such a truncation mutation in FLNC leads to an isolated cardiac phenotype, although some patients also have been described to display combined cardiac and skeletal myopathy." (PMID 37174721, 2023). "Alterations of the FLNC gene have been linked in humans to skeletal myopathies, and to cardiac abnormalities and pathologies." (PMID 32253742, 2020). "FLNC mutations have been associated with distal and myofibrillar skeletal myopathies (MFM), characterized by progressive morphological changes of the muscle fibers beginning in the Z-disc and protein aggregates in the sarcoplasm." (PMID 32295012, 2020). "Filamin C was first reported to be associated with various forms of skeletal myopathy." (PMID 35893404, 2022). "Filamin C was first reported to be associated with various forms of skeletal myopathy (i.e., MFM)." (PMID 33557094, 2021). "HspB1 has also been found to be prevalent in protein aggregates collected from patients with skeletal myopathies caused by FLNC mutations and colocalizes at sarcomeric lesions with FLNC, suggesting that it may associate with FLNC during stress." (PMID 32253742, 2020). "However, FLNC mutations are associated with myopathy with cardiac involvement or with Limb-Girdle dystrophy, a mainly skeletal muscle disorder." (PMID 24972929, 2014). "In addition, FLNC-CM patients rarely have skeletal myopathy, suggesting that the genotype–phenotype relationship of some FLNC mutations might be uncertain and needs to be further evaluated." (PMID 32295012, 2020). "DRMs are a growing class of skeletal muscle disorders caused by mutations in desmin, αB-crystallin, Z-band alternatively spliced PDZ motif, myotilin, filamin C, and Bag3." (PMID 21445271, 2011). "No skeletal myopathy was detected, which was consistent with other previously reported FLNC truncating mutation carriers." (PMID 33941202, 2021). "Therefore, FLNC has long been considered as a disease gene of primary skeletal myopathy, rarely accompanied by myocardial abnormality." (PMID 30411535, 2018).
Arrhythmia (9 papers, 2020 to 2025). Any cardiac rhythm other than the normal sinus rhythm. "Other genes include lamin A/C (LMNA), linked to a high risk of arrhythmias and sudden cardiac death, filamin C (FLNC), phospholamban (PLN), β-myosin heavy chain (MYH7), cardiac troponin T (TNT2) and desmin (DES)." (PMID 41464586, 2025). "Furthermore, various genes encoding cardiac cytoskeletal proteins such as dystrophin (DMD) for Duchenne muscular dystrophy, sarcoglycan (SGC) for sarcolemmal instability muscular dystrophy, and filamin C (FLNC) are associated with arrhythmias and SCD." (PMID 38666937, 2024). "Current recommendations advise that patients with left ventricular ejection fraction ≤ 40%, exercise-induced arrhythmias, or pathogenic variants in LMNA, TMEM43, or filamin C refrain from vigorous exercise or competitive sports, even if protected by an ICD." (PMID 41464586, 2025). "For individuals with DCM and a pathogenic/likely pathogenic variant in a gene correlated with life-threatening arrhythmias (LMNA, FLNC, RBM20, DSP), exercise should be restricted to recreational activities." (PMID 33040239, 2020).
filaminopathy (9 papers, 2016 to 2026). "A wide range of FLNC mutations are associated with various cardiomyopathies including dilated, restrictive, and hypertrophic types, and myopathies collectively termed filaminopathies." (PMID 40564978, 2025). "With the exception of one described family, filaminopathies are caused by dominant pathogenic variants in the FLNC gene." (PMID 37174721, 2023). "The expression levels of the chaperones were measured in muscle tissue from controls and five hereditary myopathies with mutations in CAPN3 (LGMD2A), FLNC (MFM-filaminopathy), DMD (Duchenne muscular dystrophy), MYOT (MFM-myotilinopathy) or VCP (IBMPFD)." (PMID 28915917, 2017). "Our previous proteomic studies identified the filamin C ratio (proportion in aggregate samples divided by proportion in control samples) as a diagnostic marker to differentiate filaminopathy from desminopathy." (PMID 26842778, 2016). "Notably, this Z-disc instability caused by FLNC mutations is intensified by acute exercise in mouse and filaminopathy patients." (PMID 39521905, 2024). "We here report on three MFM-filaminopathy patients from two families with novel truncating variants in FLNC: one in exon 30 that encodes part of Ig-like domain 15, and the other in exon 48 encoding the carboxyterminal part of dimerization domain 24 of FLNc." (PMID 37174721, 2023). "Since our findings are based on a limited number of patients, a detailed, quantitative analysis comparing autophagy and UPS marker protein levels in a larger cohort of filaminopathy patients with different categories of FLNC mutations is needed to confirm our hypotheses." (PMID 37174721, 2023). "The FLNc-associated subtype of MFM, caused by heterozygous FLNC variants (MFM5; MIM# 609524), was discovered in 2005, and subsequently an increasing number of families with MFM-filaminopathy were described." (PMID 37174721, 2023). "We believe that our results demonstrate the existence of the distinct clinical entity of filaminopathy and underscore the role of the FLNC gene in the development of pediatric RCM combined with myopathy." (PMID 36104822, 2022). "In addition, the ratio of filamin C proportions in aggregate and control samples, previously presented as marker to differentiate filaminopathy from desminopathy, is also suitable to discern filaminopathy from myotilinopathy." (PMID 26842778, 2016).
heart failure (9 papers, 2019 to 2025). Inability of the heart to pump blood at an adequate rate to meet tissue metabolic requirements. "The mutations of various genes encoding the proteins around the Z-disc, such as ANKRD1, DES, FLNC and CSRP3, are known to cause abnormal responses to mechanical stress, resulting in heart failure." (PMID 39195917, 2022). "We have also summarized the recent discovery of phosphorylation and upregulation of HspB1 in the hearts of a mouse model of heart failure alongside an interaction with FLNC, pointing to a force-dependent mode of strengthened client binding upon HspB1 phosphorylation." (PMID 32253742, 2020). "In summary, deletion of FLNC in adult cardiomyocytes led to severe DCM characterised by adverse cardiac remodelling and heart failure." (PMID 40099936, 2025). "The importance of filamin C for cardiac integrity is highlighted in two independent animal studies: cardiac-specific, and inducible FLNC knockout mouse models led to rapid DCM and heart failure." (PMID 36935760, 2023).
distal myopathy (8 papers, 2015 to 2026). Distal myopathy refers to a group of muscle diseases which share the clinical pattern of predominant weakness and atrophy beginning in the feet and/or hands. "FLNC mutation c.7123G > A, p.V2375I in the immunoglobulin (Ig)-like domain 21 can be associated with distal myopathy with typical MFM features and lower motor neuron syndrome." (PMID 31421687, 2019). "Screening of families with molecularly undetermined distal myopathy led to the identification of a c.5161delG frameshift mutation in FLNC in two members of a French family affected by distal myopathy and in one healthy relative." (PMID 29073160, 2017). "Formerly, mutations in FLNC were described as an underlying cause of two distinct types of myopathy, known as myofibrillar and distal myopathy (MFM and DM)." (PMID 26555887, 2015). "Based on similarities with previously reported findings on the FLNC c.5160delC frameshift mutation identified in Bulgarian families with distal myopathy, we propose that the novel FLNC c.5161delG (p.Gly1722ValfsTer61) mutation is responsible for the distal myopathy observed in the French family." (PMID 29073160, 2017). "This FLNC c.5161delG mutation is one nucleotide away from a previously reported FLNC mutation (c.5160delC) that was identified in patients and in asymptomatic carriers of three Bulgarian families with distal muscular dystrophy, indicating a low penetrance of the FLNC frameshift mutations." (PMID 29073160, 2017). "Filamin C is a dimeric protein encoded by FLNC (7q32), which was originally reported as a causative gene of dominant myofibrillar and distal myopathy." (PMID 39734947, 2024). "In contrast, the pathomechanisms of distal myopathy caused by FLNC frameshift mutations without myofibrillar aggregates are currently not known." (PMID 29073160, 2017). "Given these similarities, we believe that the two FLNC mutations alone can be causative of distal myopathy without full penetrance." (PMID 29073160, 2017).
gastric cancer (8 papers, 2015 to 2024). A primary or metastatic malignant neoplasm involving the stomach. "Some literature found that the CUBN and FLNC were associated with altered gastric cancer risk and involved the lymph node metastasis of gastric carcinoma, respectively." (PMID 37636564, 2023). "In contrast, another study showed that the downregulation of filamin-C by acetylated Siah2 increased the invasiveness of gastric cancer cells." (PMID 34717622, 2021).
hepatocellular carcinoma (6 papers, 2019 to 2025). A malignant tumor that arises from hepatocytes. "Also, upregulation of FLNC has been observed in advanced liver tumors: a proteomics study in hepatocellular carcinoma found FLNC levels rose with tumor stage and contributed to invasiveness." (PMID 41373405, 2025). "FLNC is a cytoskeletal protein that has been identified as a potential hepatocellular carcinoma progression marker; altered FLNC expression may lead to enhanced tumor cell motility and invasiveness." (PMID 38003580, 2023). "Some studies have shown that FLNC protein may be a target molecule for invasion and metastasis of hepatocellular carcinoma by iTRAQ technology." (PMID 32547947, 2020). "Moreover, filamin-C can interact with and activate MEK1/2 and ERK1/2 to promote the progression of hepatocellular carcinoma." (PMID 34717622, 2021).
myocarditis (6 papers, 2013 to 2025). Myocarditis is a condition that is characterized by inflammation of the heart muscle (myocardium). "The predominant pathogenic or likely pathogenic variants in patients with myocarditis were observed in the desmoplakin and filamin C genes, in contrast to patients with isolated ARVC." (PMID 39858598, 2025). "Although these studies used DSP disruption as its genetic model of myocarditis, many other genes have been implicated in this process, including TTN, LMNA, FLNC, PKP2, and others." (PMID 38768074, 2024). "In contrast to filamin A and filamin B, the high expression of filamin C in myocytes suggests that filamin C represents a sensitive and specific marker of the subclinical myocarditis that accompanies KD." (PMID 23281308, 2013). "This HRS umbrella definition therefore includes, apart from ARVC, a broad spectrum of systemic (e.g. sarcoidosis, amyloidosis), inflammatory/infectious (e.g. myocarditis, Chagas disease), and (left-dominant) genetic (e.g. Lamin A/C [LMNA], Filamin C [FLNC]) heart diseases." (PMID 38986843, 2024).
glioblastoma multiforme (5 papers, 2019 to 2024). "Filamin-C (FLNC) was associated with the risk of glioblastoma multiforme." (PMID 38259849, 2023). "FLNC, an actin cross-linking protein, is involved in cell morphology regulation and is a potential therapeutic target and biomarker for glioblastoma multiforme progression." (PMID 39013964, 2024). "High filamin-C expression has been reported to enhance the invasiveness of glioblastoma and predict poor outcomes." (PMID 34717622, 2021).